RAB33A (RAB33A, member RAS oncogene family)
Description:
The small GTPases Rab are key regulators of intracellular membrane trafficking, from the formation of transport vesicles to their fusion with membranes (By similarity). Rabs cycle between an inactive GDP-bound form and an active GTP-bound form that is able to recruit to membranes different sets of downstream effectors directly responsible for vesicle formation, movement, tethering and fusion (By similarity). Modulates autophagosome formation through interaction with ATG16L1 (By similarity).
Synonyms: RABS10
Tractability: Antibody: UniProt places it where antibodies can reach, with high confidence; its Gene Ontology location is reachable by antibodies, with medium confidence. PROTAC: ubiquitination databases record sites on it; its protein half-life has been measured.
Gene: Protein-coding gene on chromosome X (130,171,950 to 130,184,874, forward strand). Ensembl gene ENSG00000134594.
Subcellular location: Cell membrane
Subcellular location (Human Protein Atlas): Vesicles
Pathways (Reactome):
Metabolism of proteins: RAB geranylgeranylation
Vesicle-mediated transport: TBC/RABGAPs
Gene Ontology:
Molecular function: protein binding; G protein activity; GTP binding; GTPase activity
Biological process: antigen processing and presentation; autophagosome assembly; Rab protein signal transduction
Cellular component: Golgi membrane; plasma membrane
Homologues: Orthologues: dog RAB33A (100% identical), pig RAB33A (99% identical), macaque RAB33A (99% identical), rat Rab33a (99% identical), guinea pig RAB33A (98% identical), mouse Rab33a (98% identical), rabbit RAB33A (98% identical), zebrafish rab33a (75% identical), tropical clawed frog rab33a (65% identical). Paralogues in human: RAB33B (56% identical), RAB35 (38% identical), RAB30 (36% identical), RAB1A (35% identical), RAB19 (34% identical), RAB1B (34% identical), RAB39A (34% identical), RAB39B (34% identical), RAB12 (33% identical), RAB13 (33% identical), RAB8B (32% identical), RAB10 (32% identical), and 56 more.
Diseases named in the same sentence as RAB33A in open-access papers:
RAB33A is named in the same sentence as 7 diseases in open-access papers, as found by Europe PMC text mining. Sharing a sentence is not in itself a finding about the gene and the disease. The quoted sentences say what the papers report.
tuberculosis (2 papers, 2015 to 2022). A chronic, recurrent infection caused by the bacterium Mycobacterium tuberculosis. "ZNF395 is an activator of a subset of IFN-stimulated genes, and RAB33A is a T-cell regulatory molecule associated with tuberculosis that has been suggested to be involved in disease processes." (PMID 36557693, 2022).
cervical cancer (1 paper, 2025). A primary or metastatic malignant neoplasm involving the cervix. "Taken together, our results indicated the pivotal role of RAB33A in promoting cervical cancer metastasis." (PMID 40000633, 2025). "Overexpression or knockout of RAB33A was performed in HeLa and SiHa cells, two cervical cancer cell lines." (PMID 40000633, 2025). "Collectively, these results demonstrated that RAB33A promoted migration and invasion by increasing the levels of active RhoC in cervical cancer cells." (PMID 40000633, 2025). "Herein, we demonstrate that RAB33A promoted metastasis by enhancing RhoC accumulation and that higher RAB33A expression predicted poorer prognosis in patients with cervical cancer." (PMID 40000633, 2025). "Our findings reveal the crucial role of the RAB33A-RhoC axis in cervical cancer metastasis and indicate that Rho inhibitors, such as fasudil hydrochloride, may benefit a subset of cervical cancer patients." (PMID 40000633, 2025). "Next, we sought to investigate how RAB33A increases RhoC levels in cervical cancer cells." (PMID 40000633, 2025). "Our findings reveal a pivotal role of the RAB33A-RhoC axis in cervical cancer metastasis, indicating that RhoC inhibitors may be beneficial for treating cervical cancer patients with high levels of RAB33A." (PMID 40000633, 2025). "Moreover, cervical cancer patients with higher RAB33A expression according to IHC staining had shorter overall survival (OS) and distant metastasis-free survival (DMFS)." (PMID 40000633, 2025). "Interestingly, the LIR motif is also present in both the RhoA and RhoB proteins, and their levels were modestly increased by RAB33A overexpression in cervical cancer cells." (PMID 40000633, 2025). "Moreover, the colocalization of GFP and RFP puncta showed that autophagosomes accumulated when RAB33A was overexpressed in cervical cancer cells." (PMID 40000633, 2025). "Collectively, our results showed that RAB33A induced non-canonical autophagy to stabilize RhoC, which in turn promoted metastasis in cervical cancer." (PMID 40000633, 2025). "However, the autophagy induced by RAB33A overexpression in cervical cancer cells was not inhibited by 3-methyladenine (3-MA), a PI3K inhibitor, and was independent of both Beclin1 (BECN1) and WD repeat domain, phosphoinositide interacting 2 (WIPI2)." (PMID 40000633, 2025). "Conversely, in highly metastatic cervical cancer cells, RAB33A is overexpressed and induces non-canonical autophagy, recruiting TBC1D2A to inactivate RAB7, thereby inhibiting the fusion of RAB33A-induced autophagosomes with lysosomes." (PMID 40000633, 2025). "However, RAB33A inactivates RAB7, thereby inducing non-canonical autophagy to promote the accumulation of the RhoC protein, which in turn induces pseudopodia formation to promote cervical cancer metastasis." (PMID 40000633, 2025). "Additionally, TBC1D2ACC, but not TBC1D2APH or TBC1D2AGAP, colocalized with RAB33A, while only TBC1D2A∆CC did not colocalize with RAB33A; these results strongly suggested that RAB33A recruited TBC1D2A through its CC structural domain to inactivate RAB7 in cervical cancer cells." (PMID 40000633, 2025).
cancer (1 paper, 2018). A tumor composed of atypical neoplastic, often pleomorphic cells that invade other tissues. "Moreover, other genes from diverse functional groups appeared in our analysis, such as signal transducers promoting cancer growth (CD53, RAB33A, GNA11, CANX, OCRL, GIPC1, and SOS1), microtubule formation (KIF21B) and cell migration (ASAP2)." (PMID 29535628, 2018).
RAB33A also shares sentences with these, for which no sentence is quoted: Anxiety (1 paper); Arthritis (1); infection (1); melanoma (1).